CDCA4 (cell division cycle associated 4)
Diseases named in the same sentence as CDCA4 in open-access papers (continued):
Sharing a sentence is not in itself a finding about the gene and the disease.
MMR deficiencies (1 paper, 2022). "Following the discovery of a connection between CDCA4 expression and the mutation markers TMB and MSI, further research into the relationship between CDCA4 expression and carcinogenesis processes, particularly a link with MMR deficiencies, was required." (PMID 35251007, 2022).
Pan (1 paper, 2023). "Pan cancer analysis revealed that a great number of tumors highly expressed CDCA4, which was associated with poor survival and different immune infiltration characteristics." (PMID 38268722, 2023).
squamous cell carcinoma (1 paper, 2022). A carcinoma arising from squamous epithelial cells. "and colleagues found that increased CDCA4 mRNA expression was strongly related to survival in patients featuring squamous cell carcinoma of the head and neck." (PMID 36185189, 2022).
cancer (22 papers, 2012 to 2025). A tumor composed of atypical neoplastic, often pleomorphic cells that invade other tissues. "Cell division cycle-associated protein 4 (CDCA4), a protein involved in regulating the cell cycle, has a key role in cancer development." (PMID 40699773, 2025). "Previous studies conducted using cellular and animal models have demonstrated the association of CDCA4 with various malignant tumors." (PMID 38098487, 2023). "Then we integrated the results of the survival analysis in a meta-analysis, and the integrated results showed that high expression of CDCA4 was significantly associated with poor prognosis in cancer patients." (PMID 35251007, 2022). "With the exception of Thymoma (THYM), CDCA4 methylation was shown to be strongly linked with CDCA4 mRNA expression in most cancer types." (PMID 35251007, 2022). "Cell division cycle-associated protein 4 (CDCA4) is reported to function importantly during numerous human cancers development." (PMID 33613651, 2021). "Cell division cycle associated protein 4 (CDCA4) has been proved as an potential tumor promoter in various cancer types." (PMID 33436008, 2021). "Cell division cycle associated 4 (CDCA4) has been reported to be engaged into the progression of several cancers." (PMID 33436008, 2021). "In pan-cancer, a Spearman association between CDCA4 CNV and mRNA was performed." (PMID 35251007, 2022). "Moreover, despite the fact that CDCA4 expression was linked to immunity and clinical survival in human malignancies, we were unsure if CDCA4 affected clinical survival via the immune route." (PMID 35251007, 2022). "Univariate Cox regression analysis reveals that high CDCA4 expression is correlated with unfavorable prognosis in various cancers, including LIHC." (PMID 38701314, 2024). "CDCA4 expression levels in LIHC were analyzed using multiple databases including the cancer genome atlas (TCGA), gene expression profiling interactive analysis (GEPIA), and ULCAN, as well as the datasets E_TABM_36, GSE144269, GSE14520, and GSE54236." (PMID 38701314, 2024). "Cell cycle regulating proteins such as CDCA4, CDCA8, and KIF2C have been linked to tumor growth and progression, affecting the proliferation, migration, invasion and metastasis of cancer cell lines." (PMID 38605349, 2024). "Firstly, the precise significance of CDCA4 expression in various cancers and the exact implications of immune regulation in these cancers are not fully understood, as there is limited research and literature available on CDCA4." (PMID 38701314, 2024). "Using data from the TCGA database, we examined the relationship between CDCA4 expression levels and OS in various cancer types through single variate Cox regression analysis." (PMID 35251007, 2022). "More importantly, CDCA4 expression levels are not only higher universally in diverse cancer cell lines from the cancer cell line encyclopedia (CCLE) database, but also in tighter ranges when compared to the range of expression in normal tissues." (PMID 35251007, 2022). "We used GEPIA2’s “Pathological Stage Plot” module to examine the correlation between CDCA4 expression and the pathological stages of cancers." (PMID 35251007, 2022). "Future prospective research concentrating on CDCA4 expression and the tumor immune milieu would be useful in providing a conclusive answer, allowing for the development of an immuno-based anti-cancer therapy." (PMID 35251007, 2022). "In conclusion, CDCA4 is a prospective and promising therapeutic target for cancer, as well as a marker of immune infiltration and poor prognosis." (PMID 35251007, 2022). "CDCA4 expression was higher in distinct cancer types when compared to matching normal tissues, and this high expression was linked to poorer OS and DFS in those cancer types." (PMID 35251007, 2022). "To determine if this pathway has an effect on the immunological milieu of tumors, we examined the connection between CDCA4 expression and the degree of immune cell infiltration in each cancer type." (PMID 35251007, 2022).
cancer (continued). "A study of relatively normal tissues and cancers revealed that CDCA4 was strongly expressed in most tumors, with the exception of the kidney chromophobe (KICH), which revealed the opposite finding with significance." (PMID 35251007, 2022). "In the following survival analysis, cancer types with high CDCA4 expression again exhibited a worse prognosis in comparison with the low expression groups." (PMID 35251007, 2022). "In diverse cancer types, correlation analysis between CDCA4 and checkpoint gene expression indicated a high connection (P<0.05) with TNF-related immune genes including TNFRSF8, TNFRSF14, TNFRSF18, CD70, CD44, and CD276 (B7-H3)." (PMID 35251007, 2022). "In previous studies, CDCA4 was proved as a tumor promoter in various cancers, representing as an attractive therapeutic target." (PMID 33436008, 2021). "As it has been reported that CDCA4 served as a regulator of cell apoptosis via autophagy pathway in various cancers, we supposed that the regulatory mechanism of CDCA4 on cell migration and invasion partly contained regulation of autophagy." (PMID 33436008, 2021). "Its role in promoting cancer cells proliferation in other cancer types have been studied extensively, little is known about the potential role of CDCA4 in cancer progression, especially in the metastasis of NSCLC." (PMID 33436008, 2021). "Additionally, the involvement of CDCA4 in tumor occurrence, development, drug resistance, and prognosis has been observed, with its roles varying across different cancer types." (PMID 38701314, 2024). "Different roles for CDCA4 are played by different forms of cancer." (PMID 38701314, 2024). "CDCA4 has a carcinogenic impact on pan-cancer, and raising CDCA4 expression may decrease human cancer patient survival time." (PMID 35251007, 2022). "CDCA4 may serve as a biomarker for cancer immunologic infiltration and poor prognosis, providing a new way of thinking for cancer treatment." (PMID 35251007, 2022). "Moreover, we carried out molecular biology verification in HCC to further confirm the cancer promoting role of CDCA4." (PMID 35251007, 2022). "The subsequent survival analyses, which used patient data dichotomized for optimal cut off value in each cancer type, demonstrate that survival differences in OS-related cancer types were all significant, indicating that patients with high CDCA4 expression had poorer outcomes." (PMID 35251007, 2022). "CDCA4 methylation landscape in pan-cancer was also investigated." (PMID 35251007, 2022). "In addition, we investigated pathological stages and the survival analysis of CDCA4 in pan-cancer across Gene Expression Profiling Interactive Analysis (GEPIA) database." (PMID 35251007, 2022). "Our data imply that CDCA4 interacts with TIICs to alter cancer patient prognosis." (PMID 35251007, 2022). "Therefore, the results indicated that CDCA4 expression was tightly correlated with the extent of immune infiltration in cancers." (PMID 35251007, 2022). "Recently, several studies have shown that CDCA4 played various roles in different cancer types." (PMID 33436008, 2021). "In addition, the rescue assay result demonstrated that miR-497-5p repressed cancer-related functions by restraining CDCA4." (PMID 34772428, 2021). "In addition, flow cytometry results confirmed that CDCA4 significantly inhibited cancer cell apoptosis, while overexpressing miR-497-5p reversed the inhibitory effect." (PMID 34772428, 2021). "Little is known about the expression and the role of CDCA4 in cancer until now." (PMID 32913466, 2020). "Subsequently, the expressions of CDCA2, CDCA3, CDCA4, CDCA5, CDCA7, and CDCA8 genes in COAD samples across various cancer stages were verified using the GEPIA2 database." (PMID 39924497, 2025).
cancer (continued). "Targeting to CDCA4, BCL2L2, YAP1, AKT-3 and Cyclin E1, miR-15a has been found to significantly reduce cancer cell survival and aggressiveness." (PMID 30733644, 2019). "Results showed that all of the genes, except CDCA4 (positive), played a negative role across cancers." (PMID 34824999, 2021). "Additionally, the absence of significant differences in the mRNA expression levels of CDCA2, CDCA3, CDCA4, CDCA5, CDCA7, and CDCA8 across different cancer stages of COAD suggests that these genes may play a consistent role throughout the progression of COAD." (PMID 39924497, 2025).
tumor (18 papers, 2017 to 2025). "Based on several databases, we investigated the expression of CDCA4 and its association with tumor infiltrating immune cells (TIICs) and associated immunological markers, as well as the prognosis of multiple cancers." (PMID 35251007, 2022). "CDCA4 or cell division cycle-associated protein 4 is related to tumor cell proliferation and apoptosis." (PMID 34824999, 2021). "Additionally, scRNA-seq of 23 primary CRC and 10 normal mucosal samples revealed CDCA4 upregulation in tumor epithelium, with associated genes linked to DNA replication, repair, and the cell cycle, highlighting a common genomic background." (PMID 40565588, 2025). "In addition, an online tumour infiltration immune cell tool was employed to assess the association between CDCA4 expression and the clinical characteristics of LUAD." (PMID 36185189, 2022). "In addition, we pay attention to the association between the expression of CDCA4 and the use of the anti-tumor drugs." (PMID 35251007, 2022). "The data suggested that CDCA4 expression was linked with tumor infiltration levels." (PMID 35251007, 2022). "Through single-cell sequencing analysis, we found this malignant phenotype is primarily due to the high expression of CDCA4 in epithelial cells within tumor tissues." (PMID 40565588, 2025). "This analysis identified 1848 DEGs, among which CDCA4 was upregulated in the Epithelium-Tumor group." (PMID 40565588, 2025). "CDCA4 shows significant hypomethylation in tumor tissues, which explains the significant upregulation of CDCA4 in LIHC." (PMID 38701314, 2024). "By analyzing the MOD values of 80 pairs of tumor and para-tumor tissue, we found that both CDCA4 and CDCA5 are overexpressed in tumors compared with that in normal tissues (P < .001)." (PMID 38875380, 2024). "Overall, our findings revealed the critical involvement of CDCA4 in tumorigenesis and metastasis, as well as a proposed mechanism by which CDCA4 influences tumor immunology, metabolic activity, and Epithelial-Mesenchymal Transition (EMT) in malignancies." (PMID 35251007, 2022). "Raw data on CDCA4 expression in tumor samples and paracancerous samples were obtained from TCGA and GTEX databases." (PMID 35251007, 2022). "It was identified that CDCA4 expression levels in 513 tumour tissues substantially surpassed those in normal tissues based on TCGA data (P<0.001)." (PMID 36185189, 2022). "Next, immunohistochemical analysis revealed that CDCA4 was mainly located in the cytoplasm and film of tumour cells and exhibited little expression in the normal lung cells." (PMID 36185189, 2022). "The findings, particularly for KICH, LIHC, and PRAD, suggest that CDCA4 is involved in the regulation of the tumor immune response via immune checkpoint activity modulation." (PMID 35251007, 2022). "According to database analysis and identification of patient tissue samples, CDCA4 expression in tumour tissues surpassed that in normal tissues (P< 0.001)." (PMID 36185189, 2022). "The outcomes indicate that CDCA4 is closely related to tumour progression in LUAD by influencing the cell cycle." (PMID 36185189, 2022). "Only one previous study determined that CDCA4 regulates monocyte adhesion, leukocyte infiltration, and cytotoxicity of tumour cells." (PMID 36185189, 2022). "The expression levels of these hub genes, except for CDCA4, significantly decreased in BCa tissues; CDCA4 showed a remarkably upregulated role in the tumor." (PMID 34824999, 2021). "In this study, we examined the functional relevance of CDCA4-associated autophagy in NSCLC, with a focus on EMT, tumor migration and invasion." (PMID 33436008, 2021). "Regarding PAAD, increased CDCA expression along with advanced PAAD tumor stage, NUF2, CDCA2, CDCA3, CDCA4 and CDCA5 expression are risk factors for poor prognosis, while CBX2 expression is a protective factor (P < 0.05)." (PMID 33437202, 2021).
tumor (continued). "The findings of this study demonstrate that CDCA4 serves as a tumor suppressor in NSCLC, with the function of inhibiting migration and invasion of NSCLC through modulating the autophagy pathway." (PMID 33436008, 2021). "CDCA4 expression in 57 tumour tissues surpassed that in 57 matched adjacent tissues (P<0.001)." (PMID 36185189, 2022). "CDCA4 expression was shown to correlate favorably with tumor purity but negatively with TIICs." (PMID 35251007, 2022). "As indicated by these findings, CDCA4 could be key to regulating ICI in the tumour microenvironment (TME)." (PMID 36185189, 2022). "CDCA4 is known to contribute to the preservation of the Golgi architecture in tumor cells, suggesting that it may influence immune cell differentiation through the serotonin pathway." (PMID 35251007, 2022). "However, little study focused on the relationship between CDCA4 and tumour-infiltrating immune cells." (PMID 36185189, 2022). "In addition, in terms of mechanism, miR-497-5p targets 3’UTR region of CDCA4 mRNA and miR-497-5p plays an anti-tumor role by down-regulating CDCA4 level in LUSC cells, which casts light on LUSC pathogenesis." (PMID 34772428, 2021). "We found that silencing LINC01116 could hinder tumor growth, while this impact was offset by pcDNA3.1/CDCA4." (PMID 34090440, 2021). "Our data demonstrate for the first time that CDCA4-induced autophagy inhibits tumor cell migration and invasion in NSCLC, suggesting that CDCA4 may be a potential therapeutic target for NSCLC." (PMID 33436008, 2021). "Additionally, epithelial cells with elevated CDCA4 expression in tumor tissues are associated with radiotherapy resistance in CRC patients, suggesting that CDCA4 could serve as a critical therapeutic target." (PMID 40565588, 2025). "Notably, CDCA4 expression was significantly associated with tumor mutation burden (TMB) and microsatellite instability (MSI), and it plays a crucial role in regulating B cell infiltration in the tumor microenvironment." (PMID 40565588, 2025). "Compared with those in the sh‐NC group, the percentage of Ki‐67‐positive tumor tissues in the sh‐IGF2BP2 group was lower (p < 0.05), and the expression levels of IGF2BP2, circRNF20, and CDCA4 were lower (p < 0.05)." (PMID 39969065, 2025). "Across CDCA2, CDCA3, CDCA4, CDCA5, CDCA7, and CDCA8, we observed significantly lower promoter methylation levels in primary tumor samples compared to normal samples, suggesting hypomethylation of these genes in GBM tumors." (PMID 40114265, 2025). "CDCA4 expression was then analyzed using matched plots between LUAD adjacent and tumour samples from the same individuals." (PMID 36185189, 2022). "The expression levels of tumor and normal tissues were comparable in the kidney renal clear cell carcinoma (KIRC), however CDCA4 expression was lower in the KICH when compared to normal tissues." (PMID 35251007, 2022). "Consistently, significant decline in tumor volume and weight was discovered in response to LINC01116 depletion, but was reversed by pcDNA3.1/CDCA4." (PMID 34090440, 2021). "In addition, we performed qRT-PCR in vitro validation and found that APLP2,CDCA4 and VIM genes were significantly overexpressed in tumor tissues, and the expression of PTMA gene was also upregul XCated, but the difference lacked statistical significance." (PMID 38098487, 2023). "The analysis of the GOBO database in tumor mode showed that log2 expression levels of CDCA4 were altered between cell lines, but not in a specific manner." (PMID 29467944, 2018). "Notably, CDCA3, CDCA4, CDCA5, and CDCA8 exhibited elevated expression trends in the radiation-resistant cohorts, consistent with the TCGA-READ database findings showing preferential CDCA family overexpression in tumor specimens." (PMID 40565588, 2025). "Therefore, plans for further understanding the CDCA4-medicated crosstalk with TIICs in the TME are necessary, which may help understand tumour progression and develop probable therapeutic modalities." (PMID 36185189, 2022).
infection (1 paper, 2021). The state of being infected such as from the introduction of a foreign agent such as serum, vaccine, antigenic substance or organism. "Numerous CDC genes are differentially expressed in the lung tissue of mice recovering from an acute PVM infection, including Cdc20, Cdc20b, Cdca3, Cdca4, and Cdca7." (PMID 34959580, 2021).
CDCA4 also shares sentences with these, for which no sentence is quoted: acute myeloid leukemia (1 paper); Bladder Urothelial Carcinoma (1); cholangiocarcinoma (1); colorectal cancer (1); heart failure (1); mesothelioma (1); ovarian serous cystadenocarcinoma (1); Pheochromocytoma and Paraganglioma (1); polycystic ovary syndrome (1); sarcoma (1); Skin Cutaneous Melanoma (1); small cell lung carcinoma (1); uterine carcinosarcoma (1); uveal melanoma (1); Wilm’s tumour (1).